KRT9 (keratin 9)
Description:
Structural component of intermediate filaments in suprabasal keratinocytes of palmoplantar epidermis. Forms heteropolymers with a type II keratin, assembling into keratin intermediate filament networks that maintain the mechanical integrity of the palmoplantar epidermis.
Synonyms: CK-9; K9; EPPK
Tractability: PROTAC: ubiquitination databases record sites on it.
Gene: Protein-coding gene on chromosome 17 (41,565,836 to 41,572,059, reverse strand). Ensembl gene ENSG00000171403.
Pathways (Reactome):
Developmental Biology: Formation of the cornified envelope; Keratinization
Gene Ontology:
Molecular function: structural constituent of cytoskeleton; structural constituent of skin epidermis; structural molecule activity
Biological process: intermediate filament organization; skin development; epidermis development; epithelial cell differentiation; morphogenesis of an epithelium; spermatogenesis
Cellular component: extracellular exosome; extracellular region; membrane; nucleus; cytoskeleton; cytosol; keratin filament
Genetic constraint (gnomAD): Loss-of-function variants: 34 observed, 51.85 expected, observed/expected ratio (o/e) 0.66, 90% interval 0.5 to 0.87. The upper end of that interval is the gene's LOEUF score, 0.87, which puts it in group 3 of 6, group 1 being the genes least tolerant of losing a copy. Missense variants: 753 observed, 809.9 expected, observed/expected ratio (o/e) 0.93, 90% interval 0.88 to 0.99. Synonymous variants: 292 observed, 296.08 expected, observed/expected ratio (o/e) 0.99, 90% interval 0.89 to 1.09.
Homologues: Orthologues: chimpanzee KRT9 (100% identical), dog KRT9 (72% identical), macaque KRT9 (69% identical), rat Krt9 (69% identical), mouse Krt9 (68% identical), guinea pig KRT9 (54% identical). Paralogues in human: KRT10 (44% identical), KRT14 (40% identical), KRT16 (40% identical), KRT15 (38% identical), KRT24 (37% identical), KRT13 (37% identical), KRT17 (34% identical), KRT19 (34% identical), KRT12 (33% identical), KRT27 (33% identical), KRT25 (32% identical), KRT28 (31% identical), and 56 more.
Diseases named in the same sentence as KRT9 in open-access papers:
KRT9 is named in the same sentence as 55 diseases in open-access papers, as found by Europe PMC text mining. Sharing a sentence is not in itself a finding about the gene and the disease. The quoted sentences say what the papers report.
epidermolytic palmoplantar keratoderma (15 papers, 2014 to 2026). "Epidermolytic palmoplantar keratoderma (EPPK) is typically caused by variations in KRT9 or KRT1 genes." (PMID 41601798, 2026). "Mutations in Keratin-9 have been associated with epidermolytic palmoplantar keratoderma (EPPK, OMIM 144200), an autosomal dominant inherited disease." (PMID 35982790, 2022). "Mutations in KRT9 cause a rare inherited disease called palmoplantar keratoderma, which manifests as hyperproliferation." (PMID 34769520, 2021). "Correction of a dominant-negative mutation within KRT9, causing epidermolytic palmoplantar keratoderma (EPPK), was achieved using a mutation-specific CRISPR/Cas9-based strategy." (PMID 31906492, 2020). "Dominant-negative mutations in the Krt9 gene cause epidermolytic palmoplantar keratoderma, a rare skin disorder." (PMID 32545786, 2020). "Mutation of KRT9 is responsible for human epidermolytic palmoplantar keratoderma and degenerative changes of keratin’s intermediate filament structure." (PMID 24809979, 2014). "Palmoplantar keratoderma also happens to be the clinical manifestation of KRT9 deficiency." (PMID 35900871, 2022). "Consequently, genetic variants in the KRT9 gene can lead to palmoplantar keratoderma (OMIM ID:#144200) resulting in the localized fissuring of the palmoplantar epidermis." (PMID 28846680, 2017). "In humans, KRT9 is expressed solely on the palms of hands and the soles of feet, and mutations lead to a skin disorder characterized by hyperkeratosis (thickening) of the surfaces of palms and soles – epidermolytic palmoplantar keratoderma." (PMID 29035697, 2017). "KRT9, which is responsible for epidermolytic palmoplantar keratoderma, has been mainly reported to be primarily expressed in the suprabasal cells and eccrine sweat-gland ducts in the palms and soles." (PMID 39835811, 2025). "It is therefore not surprising that the pathology of KRT9 deficiency is limited to acral surfaces, such as in the case of palmoplantar keratoderma." (PMID 35900871, 2022). "Thus, deficiencies in KRT10 likely do not manifest as palmoplantar keratoderma because, at acral sites, KRT9 is the main binding partner of KRT1." (PMID 35900871, 2022).
Hyperkeratosis (4 papers, 2017 to 2025). Hyperkeratosis is a histopathological term defining a thickened stratum corneum and may be present in many different skin conditions, with many possible overlaps. "Hyperkeratosis is limited only to the palmoplantar surfaces in the case of typical PPK associated with KRT9 mutations." (PMID 33562614, 2021). "Additionally, RNase L–KO mice exhibit reduced hypodermal thickness compared with WT mice, consistent with an association of KRT9 with hyperkeratosis." (PMID 39903537, 2025). "The clinical symptom of hyperkeratosis caused by a variant in the KRT9 gene in the PPK3 family was diffuse yellow palmoplantar keratoderma, which fully corresponds with the clinical findings in a proband described by D. Fuchs-Telem—a young Ashkenazi Jewish male without a PPK family history." (PMID 36076978, 2022).
Alzheimer disease (3 papers, 2016 to 2025). A progressive, neurodegenerative disease characterized by loss of function and death of nerve cells in several areas of the brain leading to loss of cognitive function such as memory and language. "Keratin 9 was recently identified as an important component of a biomarker panel which demonstrated a high diagnostic accuracy (87%) for Alzheimer’s disease (AD)." (PMID 26973255, 2016). "A recent paper suggests that keratin 9 may serve as a biomarker for Alzheimer disease, be implicated in polycystic ovary syndrome and may serve as a marker of metastatic hepatocellular carcinoma." (PMID 29802537, 2018). "Interestingly, increased levels of KRT-9 have been found in the CSF from patients with Alzheimer’s disease, multiple sclerosis, and neuromyelitis optica compared to controls, and it has been proposed that this may be due to leakiness of the blood-brain barrier." (PMID 39164482, 2025).
melanoma (3 papers, 2018 to 2025). A malignant, usually aggressive tumor composed of atypical, neoplastic melanocytes. "Several of the EMT-related genes with higher expression in NR patients encoded for molecules controlling adhesion (ITGB3, VCAM1, collagens, and others), interaction with extracellular matrix (VEGFA, MMP14, WNT5A, LAMA1, and others), and melanoma de-differentiation (KRT9, KRT10, EGFR, and others)." (PMID 37739939, 2023). "However, recently, KRT9 has been shown to occur in many other tissues and has also been associated with bladder cancer, gastric cancer, TAMG (+) thymomas, primary melanoma, and benign nevi." (PMID 39835811, 2025). "While three of the signature genes (KLHL41, KRT9, GBP4) have not been reported so far to be expressed in melanoma, there is functional evidence for all signature genes suggesting that they might be involved in immune responses, inflammation, or tumor progression." (PMID 31360859, 2018).
bladder cancer (2 papers, 2018 to 2025). "The question as to why keratin 9 is an Hsp70 associating protein in the presence of VER and is expressed in human bladder cancer cells needs to be addressed." (PMID 29802537, 2018). "Here, we present evidence of the novel result that keratin 9 is an Hsp70 client protein and is expressed in human bladder cancer cells." (PMID 29802537, 2018). "Since the VER-treated T24 bladder cancer cell lysate contained what we suspected to be keratin 9 as a client protein of Hsp70, we wanted to confirm keratin 9 expression in other Hsp inhibitor-treated T24 bladder cancer cells by Western blot analysis." (PMID 29802537, 2018). "In order to identify Hsp70 client proteins in bladder cancer cells, a co-immunoprecipitation experiment was performed with cell lysates, and keratin 9 was identified from a lysate treated with VER155008, an Hsp70 inhibitor." (PMID 29802537, 2018). "Whatever the role(s) of keratin expression in neoplastic cells, the novel expression of keratin 9 in human bladder cancer cells adds yet another player to the complex interactions of intermediate filaments and their potential significance in the tumorigenic process." (PMID 29802537, 2018). "The expression of keratin 9 closely mimicked results which showed that muscle invasive bladder cancer cell lines were more sensitive to dual Hsp70 inhibition as compared to monotherapy with either Hsp70 or Hsp90 monotherapy agents with the exception of VER/MAL." (PMID 29802537, 2018). "Why is this protein expressed in human bladder cancer cells treated with VER155008 and what role, if any, does keratin 9 plays in the progression of bladder cancer?" (PMID 29802537, 2018).
epidermolytic hyperkeratosis (2 papers, 2022 to 2023). "To further confirm gene expression data, we immunohistochemically compared paraffin-embedded plantar PPK skin and infiltrating SCC areas of the AN patient with plantar control skin and PPK from two patients with epidermolytic hyperkeratosis due to mutations in KRT9 gene." (PMID 35854363, 2022).
gastric cancer (2 papers, 2024 to 2025). A primary or metastatic malignant neoplasm involving the stomach. "In our analysis of human-derived proteins in tongue coating, we observed a significant downregulation of KRT2, KRT9, and DCD in the tongue coating of gastric cancer patients." (PMID 38191439, 2024). "Downregulation of KRT2, KRT9, and DCD collectively indicates a decreased microbial resistance in the oral cavity of gastric cancer patients." (PMID 38191439, 2024). "A total of 5 proteins, including KRT2, KRT9, DCD, EWSR1, and CACNA1G, were downregulated in gastric cancer patients in both cohorts." (PMID 38191439, 2024). "Notably, we observed the downregulation of human keratins KRT2 and KRT9 on the tongue surface, as well as the downregulation of ABC transporter COG1136 in microbiota, in gastric cancer patients." (PMID 38191439, 2024). "Notably, we observed the downregulation of keratins KRT2 and KRT9 on the tongue surface, as well as the ABC transporter COG1136 in microbiota, in gastric cancer patients, suggesting a decrease in lingual mucosa defense ability." (PMID 38191439, 2024).
pinguecula (2 papers, 2021 to 2024). A yellowish thickened lesion on the conjunctiva near the cornea representing a benign degenerative change in the conjunctiva caused by the leakage and deposition of certain blood proteins through the permeable capillaries near the limbus. "The exception was, KRT9, which encodes a hyperproliferative-type keratin upregulated in both pterygium and pinguecula—in fact, it was among the top upregulated genes of this study." (PMID 34769520, 2021). "KRT9 is typically highly specific keratin of terminally differentiating keratinocytes of palmoplantar epidermis, but has previously been found upregulated at high levels in pterygium and pinguecula." (PMID 38368345, 2024).
viral infection (2 papers, 2014 to 2022). "Notably, keratin 2 (KRT2) and KRT9 were identified at the intersection of three gene lists, which were subgroups of the keratin family related to cell structure and integrity and might be relevant to the disease progression of viral infection-induced neuropathy." (PMID 36277496, 2022).
acral lentiginous melanoma (1 paper, 2022). A form of melanoma occurring most often on the plantar, palmar, subungual, and periungual skin. "KRT9 protein expression was significantly more likely found in acral lentiginous melanoma." (PMID 34757537, 2022).
cervical tumors (1 paper, 2025). "However, integrated HPV31 genomes from several cervical tumors overlap integration hotspots, including those on chromosomes 3 and 17 that contain the KLF5/KLF12 and KRT9/KRT14 genes, respectively." (PMID 40892869, 2025).
Harlequin ichthyosis (1 paper, 2022). Harlequin ichthyosis (HI) is the most severe variant of autosomal recessive congenital ichthyosis (ARCI; see this term). "Interestingly, some of these genes, i.e. KRT1, KRT9, KRT16, DSG1, DSC2 and JUP, are mutated in hereditary PPKs, while the ABCA12 gene is defective in harlequin ichthyosis characterized by the loss of the skin lipid barrier." (PMID 35854363, 2022).
squamous cell carcinoma (1 paper, 2023). A carcinoma arising from squamous epithelial cells. "C15orf48 had higher expression than KRT9 in squamous cell carcinoma but lower expression than KRT9 in pseudoepitheliomatous hyperplasia." (PMID 36983424, 2023). "The genes C15orf48 and KRT9 had a distinct and robust gene expression pattern in distinguishing squamous cell carcinoma from pseudoepitheliomatous hyperplasia." (PMID 36983424, 2023).
cancer (11 papers, 2008 to 2023). A tumor composed of atypical neoplastic, often pleomorphic cells that invade other tissues. "The protein with the largest fold change (10.7) was KRT9, with higher levels in samples from patients with cancer in the left colon compared to the rectum." (PMID 32452655, 2020). "A number of gene nodes linked to drug resistance in other cancer types (including CAT, TRIM59, ANXA2, ADM, AJUBA, HSPA1A/1B, LAMC2, TRIM14, KRT8, KRT18, KRT9, CLDN1, and SMARCA2) were also down-regulated in PARPis-sensitive AsPCs." (PMID 33213473, 2020). "Cancer line analysis indicated significant downregulation of five cytoskeleton proteins, keratins (KRT2, KRT9, KRT1, KRT10)." (PMID 37377864, 2023). "The experiments presented above clearly demonstrate that keratin 9 binds to Hsp70 in the presence of VER, a potent inhibitor of the Hsp70 family of chaperones which have been shown to contribute to cancer cell survival via anti-apoptotic functions." (PMID 29802537, 2018). "Levels of keratins, type I cytoskeletal 16 (KRT16), 9 (KRT9), and 10 (KRT10), as well as complement factor H‐related protein 4 (CFHR4) and 1 (CFHR1), had higher levels in plasma samples from patients with cancer in the right colon (with fold changes between 6.2‐13.0)." (PMID 32452655, 2020). "Like keratin 9, keratin 17 is not expressed in normal mature epithelia; however, it is expressed in ectodermal embryonic stem cells and in carcinomas." (PMID 29802537, 2018). "Besides, these genes, ADAMTS2, KRT9, KRT13, LY6D, had been reported in a variety of cancers." (PMID 35237592, 2022).
tumor (10 papers, 2013 to 2023). "Immunohistochemistry of primary tumor tissue was performed for eight proteins: COL6A6, DCD, GBP4, KLHL41, KRT9, PIP, SCGB1D2, SCGB2A2." (PMID 34757537, 2022). "By contrast, SEMA4B, KRT1, KRT9, FBLN1, and PTGDS are involved in the anti-invasive activity of tumor cells." (PMID 32953262, 2020).
infection (6 papers, 2014 to 2025). The state of being infected such as from the introduction of a foreign agent such as serum, vaccine, antigenic substance or organism. "After 48 hours post-infection, we found that overexpression of wild-type KRT9 maintained the suppression of RSV replication (lanes 1–3), but the △202–302 mutant failed (lane 4)." (PMID 39835811, 2025). "For further revealing the role of KRT9 in the GBP5 anti-RSV process, endogenous KRT9 knockdown HEK293T cells were overexpressed with the wild-type or a 202–302 deletion mutant of KRT9 and infected with RSV at 0.1 multiplicity of infection." (PMID 39835811, 2025). "After 48 hours post-infection, we found that KRT9-Myc did not decrease RSV-N expression individually (lanes 2 and 5)." (PMID 39835811, 2025). "In A549 infection, KRT9 knockdown did not affect RSV-N expression without IFN-γ treatment (lanes 2 and 5); however, it was affected with IFN-γ treatment (lanes 3 and 6)." (PMID 39835811, 2025).
KRT9 also shares sentences with these, for which no sentence is quoted: Palmoplantar keratoderma (7 papers); skin disorder (3); epidermolysis bullosa simplex (2); pachyonychia congenita (2); pterygium (2); thymoma (2); adenoid cystic carcinoma (1); angioleiomyoma (1); basal cell carcinoma (1); colon carcinoma (1); cutaneous melanoma (1); diabetes (1); epidermolytic ichthyosis (1); epilepsy (1); gallbladder carcinoma (1); gout (1); hepatocellular carcinoma (1); Hyperglycemia (1); Jaundice (1); keratoconus (1); latent infection (1); lichen simplex chronicus (1); lymphoma (1); multiple sclerosis (1); myopericytoma (1); nasopharyngeal carcinoma (1); neurinoma (1); neuroblastoma (1); neurodegenerative disease (1); neuromyelitis optica (1).
A further 9 diseases each share a sentence with KRT9 in 1 paper.